PPARA (peroxisome proliferator activated receptor alpha)
Diseases named in the same sentence as PPARA in open-access papers (continued):
Sharing a sentence is not in itself a finding about the gene and the disease.
hepatoblastoma (2 papers, 2005 to 2019). Hepatoblastoma (HB) is a malignant hepatic tumor and is the most common pediatric liver cancer. "Previously, selective up‐regulation of human PANK1α transcription by a PPARα agonist, bezafibrate, was reported in cultured hepatoblastoma cells." (PMID 31660701, 2019). "In the real-time PCR analyses PPARα was more effective than other subtypes in the hepatoblastoma cell lines, although all subtypes could induce the expression of these genes." (PMID 16197558, 2005).
Hepatomegaly (2 papers, 2017 to 2024). Abnormally increased size of the liver. "Hepatomegaly is also a known effect of PPARα agonism in rodents and in the present study a further increase (71%) in liver weight in AZD6610‐treated BTBRob/ob mice was also observed." (PMID 28292877, 2017).
hyperhomocysteinemia (2 papers, 2016 to 2021). A serious metabolic condition caused by mutations in the MTHFR gene, medications, or nutritional deficiency. "In addition, hyperhomocysteinemia reduced the expression of anti-inflammatory genes, i.e., PPARγ and PPARα in human monocytes." (PMID 34771080, 2021). "Notably, fibrate treatment was previously shown to increase plasma tHcy, supporting a possible role of PPARα in the hyperhomocysteinemia in response to TTP treatment." (PMID 26846427, 2016).
ischemia reperfusion injury (2 papers, 2016 to 2025). Adverse functional, metabolic, or structural changes in ischemic tissues resulting from the restoration of blood flow to the tissue (reperfusion), including swelling; hemorrhage; necrosis; and damage from free radicals. "Leucine accumulation, resulting from impaired BCAA metabolism, triggers both mTOR-mediated cell death and PPARα-enhanced FA oxidation, leading to increased cardiac lipid toxicity and vulnerability to ischemia-reperfusion injury." (PMID 40182633, 2025).
ischemic cardiomyopathy (2 papers, 2016 to 2022). Ischemic cardiomyopathy is a cardiomyopathy in which a weakness in the muscle of the heart due to inadequate oxygen delivery to the myocardium with coronary artery disease being the most common cause. "Cardiac remodeling occurring in patients with end-stage heart failure due to ischemic cardiomyopathy is related to PPAR activity, whereby inactivation of PPARα and PPARγ would lead to an increase in the production of ET-1 and the presence of cardiac fibrosis." (PMID 27293418, 2016).
liver dysfunction (2 papers, 2024 to 2025). "The authors hypothesized that pemafibrate improves liver dysfunction by decreasing the TG content in the liver via β-oxidation of free fatty acids with activation of PPARα." (PMID 41237431, 2025).
long chain acyl-CoA dehydrogenase deficiency (2 papers, 2010 to 2024). A genetic disorder characterized by deficiency of the enzyme long-chain acyl-coenzyme A dehydrogenase that metabolizes long-chain fatty acids. "MK886, an inhibitor of PPARα, induced a decrease in serum sulfatides levels in skin cells from patients with very long-chain acyl-CoA dehydrogenase deficiency and excessive fatty acid accumulation activated PPARα and increased sulfatides levels." (PMID 38943216, 2024).
lymph node metastasis (2 papers, 2019 to 2021). "However, PPARα expression was not related to sex, age, lymphatic invasion, venous invasion, lymph node metastasis, depth of invasion and stage." (PMID 34572440, 2021).
metabolic (2 papers, 2020 to 2025). "Therefore, melatonin alleviates glycolipid metabolism disorders by activating the AMPKα/PPARα signaling pathway, reducing lipid deposition in the liver and adipose tissues, and increasing insulin sensitivity." (PMID 33150187, 2020).
neuropathic pain (2 papers, 2015 to 2021). Chronic pain caused by damage to nerve fibers. "In neuropathic conditions, the PPARα agonists GW7647 and palmitoylethanolamide (PEA) managed to attenuate hyperalgesia, whereas these actions were absent in PPARα knock-out neuropathic pain mice." (PMID 34202590, 2021).
Opportunistic infection (2 papers, 2007 to 2022). An infection that is caused by a pathogen that would generally not be able to cause an infection in a host with a normal immune system. "Accordingly, it can be speculated that exposure to PPARα activators may exacerbate the condition of individuals infected with the HIV virus by contributing to an immune environment favorable for enhanced viral replication and opportunistic infections." (PMID 18566640, 2007).
pancreatic adenocarcinoma (2 papers, 2021 to 2025). "Increased expressions of ACAA1 (acetyl-CoA acyltransferase 1), FABP1 (fatty acid-binding protein 1), PPARA, and FABP2 genes were seen in ampullary adenocarcinomas compared to pancreatic adenocarcinomas." (PMID 33390794, 2021).
peritonitis (2 papers, 2020 to 2023). Inflammation of the peritoneum (tissue that lines the abdominal wall and covers most of the organs in the abdomen). "Together, these data demonstrate that by manipulating PPARα expression levels and function, mice can be protected or sensitized for CLP‐induced peritonitis." (PMID 31916705, 2020).
retinal diseases (2 papers, 2020 to 2025). "Recently, it has been reported that the PPARα/γ dual agonist saroglitazar, developed by Zydus cadila and approved in India, is patented for treating retinal diseases caused by inflammation, macular degeneration, and neovascularization." (PMID 33291567, 2020). "The combination of PPARα modulators with small molecules offers an interesting perspective for retinal diseases’ therapy." (PMID 39941353, 2025). "Herein, we summarize recent findings for PPARα agonists in the therapeutic treatment of retinal diseases." (PMID 33291567, 2020). "Taken collectively, the multidimensional benefits of enhanced PPARα activity provide compelling evidence that PPARα agonism is capable of addressing the complex nature of common retinal diseases beyond what is capable with anti-VEGF strategies." (PMID 33291567, 2020). "PPARα is the most studied isoform with respect to retinal diseases, with published results tracking back to 1969." (PMID 33291567, 2020). "Fenofibrate is the most studied PPARα agonist for treating retinal diseases." (PMID 33291567, 2020). "These cumulative observations suggest PPARα agonism will manifest pleiotropic downstream effects such as anti-apoptosis, anti-inflammation, and anti-oxidation—all of which would be beneficial to addressing the complex nature of prevalent retinal diseases." (PMID 33291567, 2020). "Although the fenofibrate results provide compelling evidence that PPARα agonism by systemically administered small molecules is a clinically validated avenue for the treatment of retinal diseases, new PPARα agonists with improved pharmacokinetic and pharmacodynamic profiles are required." (PMID 33291567, 2020).
Shock (2 papers, 2020 to 2022). The state in which profound and widespread reduction of effective tissue perfusion leads first to reversible, and then if prolonged, to irreversible cellular injury. "In children with septic shock decreased PPARα expression in whole blood correlates with severity." (PMID 32154187, 2020).
Wilson disease (2 papers, 2020 to 2022). A very rare inherited multisystemic disease presenting non-specific neurological, hepatic, psychiatric or osseo-muscular manifestations due to excessive copper deposition in the body. "In patients with Wilson’s disease, PPARα expression was found to be altered in proportion to the progression of liver injury, i.e., it was enhanced in patients with mild liver impairment but reduced in patients with moderate or intense liver damage." (PMID 36139455, 2022).
Alport syndrome (1 paper, 2025). A rare renal disease characterized by glomerular nephropathy with hematuria progressing to end-stage renal disease (ESRD), frequently associated with sensorineural deafness, and occasionally with ocular anomalies. "Using a mouse model of Alport syndrome, we show that nicotinamide riboside (NR), an NAD+ precursor, stimulated renal PPARα signaling and restored FAO in the proximal tubules, thereby protecting from CKD in both sexes." (PMID 40059824, 2025).
altitude sickness (1 paper, 2019). Multiple symptoms associated with reduced oxygen at high altitude. "Genomic studies have identified robust signals of positive selection across EPAS1, EGLN1, and PPARA, that are associated with hemoglobin levels, which likely protect the Sherpa from altitude sickness." (PMID 31555147, 2019).
ampullary adenocarcinomas (1 paper, 2021). "The heatmap of gene expression rankings indicated that PPARA and lipid metabolism-related genes were highly expressed in ampullary adenocarcinomas compared to periampullary adenocarcinomas." (PMID 33390794, 2021). "A heatmap study of GSE39409 further supported PPARA and lipid metabolism-related genes being highly correlated with carcinogenesis of ampullary adenocarcinomas, but not other periampullary adenocarcinomas." (PMID 33390794, 2021).
anorexia nervosa (1 paper, 2016). A disorder most often seen in adolescent females characterized by a refusal to maintain a minimally normal body weight, an intense fear of gaining weight, a disturbance in body image, and, in postmenarcheal females, the development of amenorrhea. "Of those nine genes, AKAP6 and NTNG1 were genes associated with anorexia nervosa and the remaining seven (AGT, CD36, CD38, FOXP1, PPARA, PPARG and SELL) were selected for their relationship with T2D." (PMID 27483138, 2016).
aortic aneurysm (1 paper, 2022). A ruptured aneurysm located in the wall of the proximal portion of the descending aorta proceeding from the arch of the aorta. "It has been reported that fenofibrate, a major conventional PPARα agonist, reduces aortic dilatation in murine models of aortic aneurysms." (PMID 35845076, 2022).
Atrophy (1 paper, 2025). Any weakening or degeneration, especially through lack of use. "Thus, the core role of the FAPs‐leptin‐PPARα axis in regulating intramuscular lipid metabolism, as revealed in this study, provides important insights into the pathophysiological mechanisms underlying human disuse muscle atrophy." (PMID 41305914, 2025).
biliary atresia (1 paper, 2022). A rare, biliary tract disease characterized by progressive obliterative cholangiopathy of the intra- and extrahepatic bile ducts, occurring in the embryonic/ perinatal period, leading to severe and persistent neonatal jaundice and acholic stool. "Bioinformatics analysis showed that the expression of PPARα, CYP7A1 and NR1H4 (FXR) in the biliary atresia group was significantly lower than in the control group." (PMID 36090996, 2022). "The downregulation of PPARα and NR1H4 (FXR) signaling pathway may be closely related to biliary atresia." (PMID 36090996, 2022).
brain glioma (1 paper, 2018). A malignant glioma that involves the brain. "Our study extends these findings by showing that miR-214 targeting of E2F2 inhibits the proliferation of human brain glioma cells through a PPARα-regulated pathway." (PMID 29862267, 2018).
chronic hepatitis B (1 paper, 2016). "To investigate whether CHOP and PPARα are associated with the progression of ALF in individuals with HBV infection, we quantified the expression of CHOP and PPARα in liver tissues of control subjects, individuals with chronic hepatitis B (CHB) and individuals with HBV-related ALF." (PMID 27482818, 2016).
citrin deficiency (1 paper, 2025). "Dyslipidemia and steatogenesis in patients with citrin deficiency have also been associated with PPARα downregulation, but the mechanisms behind this downregulation remained elusive." (PMID 41132685, 2025).
citrullinemia (1 paper, 2022). Citrullinemia is an autosomal recessively inherited disorder of urea cycle metabolism and ammonia detoxification characterized by elevated concentrations of serum citrulline and ammonia. "In the patients with citrullinemia, the main regulator of fatty acid oxidation, peroxisome proliferator-activated receptor α (PPARα), had been observed to be downregulated." (PMID 36090036, 2022).
cutaneous leishmaniasis (1 paper, 2013). Leishmaniasis affecting the skin. "Thus, cutaneous leishmaniasis caused by L. major could be alleviated with PPARα and PPARγ ligands in murine models." (PMID 23555077, 2013).
eating disorder (1 paper, 2014). A broad group of psychological disorders with abnormal eating behaviors leading to physiological effects from overeating or insufficient food intake. "Administration of OEA produced satiety and reduced weight gain in wild-type mice, but this response was abolished in PPARα-null mice, suggesting that PPARα regulates the feeding behavior and may be a potential target for treating eating disorders." (PMID 24693278, 2014).
eczema (1 paper, 2012). "Mice deficient in the PPARα gene are more likely to develop eczema-like skin lesions upon antigen sensitization, suggesting that the expression of this gene is more likely to protect against, rather than induce, eczema." (PMID 22732598, 2012).
edema (1 paper, 2026). An abnormal accumulation of fluid beneath the skin, or in one or more cavities of the body. "Here, we report that fenofibrate (FFB), an agonist of the nuclear receptor peroxisome proliferator-activated receptor-α (PPARα), alleviates post-traumatic brain edema by enhancing blood-brain barrier (BBB) integrity in a mouse model of severe TBI." (PMID 42208263, 2026).
gastritis (1 paper, 2024). Inflammation of the stomach. "Then we retrieved the PDB database and obtained the protein 7F8V contained in the gene GAST related to gastritis and the protein 6LXA contained in the gene PPARA related to fatty liver." (PMID 39563444, 2024). "Specifically, we first retrieved the MalaCards database to obtain the genes with the highest scores associated with gastritis and fatty liver, namely GAST and PPARA." (PMID 39563444, 2024).
Gilbert syndrome (1 paper, 2025). An autosomal recessive inherited disorder characterized by unconjugated hyperbilirubinemia, resulting in harmless intermittent jaundice. "This was also found in people with the Gilbert’s syndrome polymorphism, who had increased PPARα and ATP-dependent AMP-activated protein kinase (AMPK), which they concluded were associated with leaner body weights and improved insulin sensitivity." (PMID 39873298, 2025).
glomerulonephritis (1 paper, 2012). A renal disorder characterized by damage in the glomeruli. "Recently, we reported that PPARα in activated mesangial cells exerted anti-inflammatory effects and that the deficiency of PPARα resulted in high susceptibility to glomerulonephritis." (PMID 22675338, 2012). "Moreover, we also showed that a deficiency of PPARα resulted in high susceptibility to glomerulonephritis in an in vivo murine study." (PMID 22675338, 2012). "We believe that the results are important when considering the beneficial potential of PPARα-related medicine in treating glomerulonephritis." (PMID 22675338, 2012). "Nevertheless, the potential anti-nephritic effects of PPARα activation suggested in the current study will be valuable for the development of a useful therapeutic strategy to treat glomerulonephritis." (PMID 22675338, 2012). "Another earlier experimental study using a rat antiglomerular basement membrane crescentic glomerulonephritis model also indicated the direct anti-inflammatory effects of PPARα, thus supporting our results." (PMID 22675338, 2012). "Therefore, this animal model appeared to be suitable to demonstrate the direct anti-inflammatory effects of PPARα in glomerulonephritis." (PMID 22675338, 2012).
gynecologic cancers (1 paper, 2023). "Another interesting result in the present study was that the expression of ARID1A, a key subunit of the SWI/SNF complex and a common tumor suppressor gene frequently mutated in gynecologic cancers, positively correlated with the expression of PPARα." (PMID 37305395, 2023).
herpesvirus infection (1 paper, 2023). "Importantly, the effects of WY14643 on herpesvirus infection and interferon response are independent of PPARα." (PMID 36715509, 2023).
hyperaldosteronism (1 paper, 2018). Overproduction of aldosterone by the adrenal glands, which may lead to hypokalemia and/or hypernatremia. "Hence, blockade of PPARα signalling may have translational potential in regulating human hyperaldosteronism, although this strategy may be sex limited." (PMID 29222092, 2018).
Hyperoxaluria (1 paper, 2016). Increased excretion of oxalates in the urine. "Therapeutic effects of the PPARα agonist fenofibrate and PPARγ agonist pioglitazone were also assessed in a 1% ethylene glycol-induced rat model of hyperoxaluria." (PMID 27022389, 2016).
Hypoinsulinemia (1 paper, 2015). A decreased concentration of insulin in the blood. "In non-ruminant liver, hypoinsulinemia due to undernutrition increases NEFA flux into liver where they activate PPARα and forkhead box A2 (FOXA2) resulting in an overall increase in fatty acid oxidation and ketogenesis." (PMID 26451842, 2015).
invasive breast carcinoma (1 paper, 2016). A carcinoma that infiltrates the breast parenchyma. "Although there has been significant interest in understanding the role of PPARα in metabolic disorders, there are only a few reports on PPARα in human malignant diseases especially inflammatory and invasive breast cancer." (PMID 26621841, 2016).
irritation (1 paper, 2010). "The endogenous PPARα ligand 8S-HETE, which is produced by 8S-LOX after skin irritation, induces keratinocyte differentiation and PPARα-mediated transcription." (PMID 21297902, 2010).
Lipedema (1 paper, 2022). Disorder of adipose tissue characterized by symmetric and bilateral enlargement of the lower extremities due to abnormal deposition of subcutaneous fat often in obese women. "PPARA activation prevents inflammation in white adipose tissue, therefore a mutation in this gene could increase inflammation in lipedema tissue." (PMID 35207755, 2022). "This may indicate an involvement of PPARA in the development of lipedema." (PMID 35207755, 2022).
lymphoid leukemia (1 paper, 2008). A malignant lymphocytic neoplasm of B-cell or T-cell lineage involving primarily the bone marrow and the peripheral blood. "Previously, we showed that human myeloidand lymphoid leukemia cells express PPARα and PPARγ; ligands, such as troglitazone, inhibited their cell growth." (PMID 18528521, 2008). "Furthermore, we have found that a dual PPARα/γ ligand (TZD18) has the ability to induce marked apoptosis and toinhibit growth of lymphoid leukemia cells." (PMID 18528521, 2008).
macrosomia (1 paper, 2026). "Lower serum PPARα protein levels in early pregnancy may be associated with a reduced risk of macrosomia, particularly in non-obese women." (PMID 41727219, 2026).
macular edema (1 paper, 2021). "Oral administration of fenofibrate, a PPARα agonist, has shown therapeutic effects on macular edema and retinal neovascularization in diabetic patients." (PMID 34943243, 2021). "Clinical studies showed that fenofibrate, a PPARα agonist, has robust therapeutic effects on macular edema and retinal neovascularization after oral administration." (PMID 34943243, 2021).